CD24 (CD24 molecule)
Diseases named in the same sentence as CD24 in open-access papers (continued):
Sharing a sentence is not in itself a finding about the gene and the disease.
ovarian carcinoma (continued). "Two cargo proteins, CD24 and EpCAM, were found in exosomes from malignant ascites of patients with ovarian cancer." (PMID 36741380, 2022). "CD24 also played a role in immune regulation as an inhibitory factor to mediate immune escape via interaction with Siglec-10 on macrophages in breast and ovarian cancers, suggesting its critical biological function in cancer development." (PMID 36612229, 2022). "The recent identification of epithelial cell adhesion molecules and CD24 in ovarian cancer-derived EVs has emerged as a promising alternative for the early detection of ovarian cancer." (PMID 36407096, 2022). "Other studies have found that L1 cell adhesive molecules can effectively inhibit the spread of ovarian cancer cells, and CD24 protein is a biomarker of poor prognosis of ovarian cancer." (PMID 36741380, 2022). "Upregulated expression of CD24 on cancer cells is closely related to the prognosis of ovarian cancer and triple-negative breast cancer." (PMID 37551166, 2022). "In vitro, dual blockade of CD47 and CD24 exhibited an additive effect on ovarian cancer cell phagocytosis." (PMID 35020853, 2022). "CD24 and epithelial cell adhesion molecule (EpCAM) proteins were identified in exosomes purified from ascites fluid of ovarian cancer patients." (PMID 35024437, 2022). "For instance, the CD44+/CD24- ovarian cancer cells have CSC-like properties such as tumor-initiating ability and invasion." (PMID 34064635, 2021). "A separate hierarchical cluster of immature or stem-like cell populations (n = 4) was identified, which expressed CD133, CD34, or both, as well as CD24, a marker found on both immature leukocytes and ovarian cancer cells." (PMID 33670410, 2021). "Blockade of CD24-Siglec-10 signaling is a potential therapeutic strategy for breast and ovarian cancer immunotherapy." (PMID 33763066, 2021). "Using CyTOF, CD24 was previously used to grade ovarian cancer, cytokeratin was applied in labeling melanoma cells, and EpCAM was recently selected for labeling of ovarian carcinoma cells." (PMID 35008313, 2021). "CD24 can be the dominant innate immune checkpoint in ovarian cancer and BC and is a promising target for cancer immunotherapy." (PMID 33670444, 2021). "The overexpression of CD24 has been reported in ovarian cancer patients, and it is a metastatic prognosis marker for poor survival." (PMID 34064635, 2021). "The anti-CD24.CAR-NK92 cells were found to be highly active against CD24-expressing ovarian cancer cell lines (SKOV3, OVCAR-3) and patient-derived cells." (PMID 34072732, 2021). "Genetic depletion of either CD24 or Siglec-10 or blockade of the CD24–Siglec-10 interaction by monoclonal antibodies can markedly augment the phagocytosis of human breast and ovarian cancer cells." (PMID 34207286, 2021). "Triple-positive (CD24+/CD44+/EpCAM+) cells isolated from ovarian cancer patients exhibit clonogenic potential and chemoresistance to cisplatin and doxorubicin." (PMID 34064635, 2021). "In contrast, the cell aggregates found in most ovarian cancer samples contained a much higher (> 80%) percentage of tumor cells showing a strong EpCAM expression or combined EpCAM and CD24 positivity." (PMID 34060699, 2021). "CD24 is one of the ovarian cancer stem cell markers, and the overexpression of CD24 in OCs was associated with a more aggressive phenotype and increased metastasis and invasion capacity." (PMID 33583413, 2021). "Many efforts have been done for early intervention about CD24 target in the prevention and treatment of cancer, such as colorectal cancer, pancreatic cancer, ovarian cancer and bladder cancer." (PMID 33424840, 2020). "The cellular target for CD24 is Siglec-10 present on TAMs in ovarian cancer, but expressed at low levels on peripheral blood mononuclear cells and peritoneal macrophages from patients without cancer." (PMID 32937961, 2020).
ovarian carcinoma (continued). "Ovarian cancer stem cells (CSCs), also known as cancer-initiating cells, are characterized by cell surface expression of CD24, CD44, CD117 (KIT), SOX2, and NANOG." (PMID 32823589, 2020). "An additional “don’t eat me” signal, and perhaps the most dominant innate immune checkpoint for ovarian cancer has recently been identified as CD24." (PMID 32937961, 2020). "Our results suggest that CD24 is a promising tumor target for FIGS in ovarian cancer patients, as it fulfils the requirements of a good biomarker for the development of FIGS contrast agents." (PMID 33260974, 2020). "CD24 can be the dominant innate immune checkpoint and novel “Don’t Eat Me” signal that promotes ovarian cancer and breast cancer immune escape." (PMID 33424840, 2020). "Some cancer cells insensitive to CD47 signal blocking turned out to be sensitive to CD24 blocking, such as ovarian cancer." (PMID 33597922, 2020). "In ovarian cancer, CD24+ CSCs were reported to be less proliferative and more resistant to chemotherapy compared to CD24− cells." (PMID 31446534, 2020). "As an example, a 3D‐nanopatterned microfluidic chip allowed for the detection, in 2‐μL plasma samples from ovarian cancer patients, of exosome subpopulations expressing CD24, EpCAM and FR‐α proteins as potential biomarkers for ovarian cancer." (PMID 32666618, 2020). "CD24 expression in ovarian cancer has been found to correlate with clinicopathological parameters, such as higher tumor grade, higher tumor stage, omental metastasis, relapse, and a more aggressive course of the disease." (PMID 33260974, 2020). "This microfluidic chip was used for the rapid detection of exosomes expressing CD24, EpCAM and folate receptor α (FRα) in only 2 μL of plasma from ovarian cancer patients and healthy controls." (PMID 32226524, 2020). "Phosphorylated signal transducer and activator of transcription 3 (STAT3), which is found primarily in CD24+ tumor cells, promotes the self-renewal capacity of ovarian cancer CSCs, which also express higher mRNA levels of stemness genes." (PMID 33260974, 2020). "In vitro experiments have shown that phagocytosis by donor-derived macrophages is increased significantly against ovarian cancer patient cells treated with a CD24 mAb compared to CD47 mAb treatment and control." (PMID 32937961, 2020). "Using a threshold of 25% CD44+/CD24–ve ovarian cancer cells found in ascites, patients with >25% CD44+/CD24−ve were significantly more likely to have recurrence (83 vs. 14%, P=0.003) and had shorter median progression-free survival (6 vs. 18 months, P=0.01)." (PMID 32684928, 2020). "In fact, direct involvement of CD24 in P-selectin mediated tumor–mesothelial adhesion in ovarian cancer has already been demonstrated." (PMID 32785160, 2020). "In recent years, various specific markers of stemness, including CD44, CD117, aldehyde dehydrogenase (ALDH), CD133, CD24, and the epithelial cell adhesion molecule (EpCAM), have been used to isolate and characterize ovarian cancer stem cells." (PMID 31261739, 2019). "The authors analyzed EVs derived from different ovarian cancer cell lines and found EpCAM and CD24 as markers to distinguish among ovarian cancer-derived EVs." (PMID 30872565, 2019). "To determine the general significance of CD24 amplification and cancer prognosis, we also analyzed the correlation between CD24 gene copy number and mRNA expression among prostate, lung and ovarian cancer, all known to overexpress CD24." (PMID 31244889, 2019). "CD24 amplification was observed at a high rate among ovarian cancer (20.3%) and lung cancer (19.6%), while prostate cancer rarely (0.4%) showed CD24 amplification." (PMID 31244889, 2019). "By using a 3D novel engineered ExoProfile chip, diagnostic power of seven markers (EGFR, HER2, CA125, FRα, CD24, EpCAM, and CD9 plus CD63) were evaluated with AUC = 1 in ovarian cancer derived exosomes." (PMID 31718609, 2019).
ovarian carcinoma (continued). "It has been postulated that while human ovarian cancer stem cells are CD24+CD44+, human embryonal carcinoma stem cells are CD133+SSEA4+." (PMID 30375490, 2018). "“ExoSearch” chip was used for liquid biopsy of ovarian cancer by measuring three exosomal tumor protein markers such as CA-125, EpCam and CD24." (PMID 28085080, 2017). "nPLEX has been used to differentiate ascites samples from ovarian cancer patients from healthy controls as ovarian cancer cell-derived exosomes were identified for their expression of CD24 and EpCAM." (PMID 28085080, 2017). "Three exosomal tumor markers (CA-125, CD24 and EpCAM) were used to isolate exosomes from ovarian cancer patient plasma." (PMID 29262670, 2017). "In ovarian cancer, the most common CSCs identified include CD24, CD34, CD44, CD117, ALDH1, EpCAM, SSEA4, NANOG, MYD88, and SOX2 positive cells." (PMID 29190952, 2017). "These ovarian cancer stem-like cells overexpressed specific ovarian cancer stem cell markers including CD24, CD44, CD117, CD133 and ALDH." (PMID 28459431, 2017). "Recent discoveries of epithelial cell adhesion molecule (EpCAM) and CD24 in ovarian cancer-derived exosomes have been highly promising alternatives for early detection of ovarian cancer." (PMID 28851367, 2017). "Cytoplasmic CD24 expression has been identified as a marker of poor prognosis in gastric cancer, colorectal cancer, ovarian cancer and malignant neoplasms of the salivary glands." (PMID 27414409, 2016). "In further support of PD-L1 control of stemness genes, the ovarian cancer TIC genes cd24, cd117 (c-Kit) and lin28a23 and additional TIC genes nes and ck18 were significantly reduced in total ID8agg PD-L1lo versus control cells by RNA sequencing." (PMID 28798885, 2016). "For example, in ovarian cancer, higher levels of CD24 indicate worst prognosis and reduce patient survival rates." (PMID 25883534, 2015). "This study illustrated that targeting CD24 with a monoclonal antibody inhibits tumour growth in xenograft models of lung and ovarian cancers via changes in tumour cell proliferation and angiogenesis." (PMID 26444008, 2015). "A study showed that levels of EpCAM and CD24 present in exosomes were correlated with the aggressiveness of ovarian cancer." (PMID 25883534, 2015). "Concerning glycoproteins, exosomes derived from ovarian cancer patients carry the putative cancer marker glycosylated molecules CD24 and EpCAM, supporting their potential in diagnostics." (PMID 26248080, 2015). "In epithelial ovarian cancer high scores of cytoplasmic CD24 were highly predictive of shorter patient survival times (mean 97.8 vs. 36.5 months), whereas membranous CD24 expression seemed to have no influence on survival times." (PMID 26578846, 2015). "Recent discoveries of the presence of microRNAs, epithelial cell adhesion molecule (EpCAM) and CD24 in ovarian tumor-derived exosomes have been highly promising alternatives for early detection of ovarian cancer." (PMID 24460816, 2014). "Recent studies have identified CD24 as a marker in cancer stem cells in several cancers, including pancreatic cancer, colorectal cancer-derived cell lines, and ovarian cancer." (PMID 24612587, 2014). "CD44+ cells, including CD44+MyD88+ cells from either ascites or tumor tissues and CD44+CD24+EpCAM+ cells from ovarian cancer cell lines, exhibit the molecular phenotypes of ovarian CSC/TICs." (PMID 23528891, 2013). "In this context, few previous studies have demonstrated the existence of CSC-enriched side population of cells or CD44, CD117, CD133, CD24 enriched population of cells in ovarian cancer cell lines or ovarian cancer patient’s samples." (PMID 23537295, 2013). "Apart from CD44, many studies refer CD24 with vital role in ovarian cancer metastasis, and it can be used as a potential CSC marker." (PMID 22693526, 2012). "With critical review of literature, it appears that the importance of CD44 and CD24 expression in ovarian cancer is more debatable." (PMID 22693526, 2012).
ovarian carcinoma (continued). "Some of the most commonly identified markers are CD133, CD44, and CD24, which are found in breast, prostate, pancreas, and ovarian cancer." (PMID 21904548, 2011). "Recently, CD24 hasbeen investigated in the context of ovarian cancer stem cells although the data arecontroversial as both the presence and absence of CD24 has been shown to beassociated with a stem cell population in ovarian cancer." (PMID 21423607, 2011). "Exosomes in the ascites derived from ovarian cancer carried the marker set EpCAM, CD24 and CD9 that appear to exist on a common exosome type." (PMID 21651777, 2011). "CD24 staining intensity in gastric, breast, colon, gallbladder and ovarian cancer correlate with lymph node metastasis." (PMID 21676268, 2011). "It has been shown that the ovarian cancer proteins CD24 and EpCAM can indeed be found in exosomes from ascites fluid of ovarian cancer patients." (PMID 19619303, 2009). "Our recent description of CD24 expression as an independent marker of shortened patient survival in epithelial ovarian cancer further underscores the importance of CD24 in metastatic disease progression of human carcinomas." (PMID 12610508, 2003). "Recently, we described CD24 as an independent prognostic marker of shortened patient survival in ovarian cancer." (PMID 12610508, 2003). "This paradoxical phenotype suggests that NK cell-based immunotherapeutic interventions could be a promising avenue to surmount chemoresistance observed in CD24-positive ovarian cancer cells." (PMID 40486886, 2025). "In lung and ovarian cancer models, targeting CD24 with SWA11 monoclonal antibody effectively delayed the growth of xenografts, reduced blood vessel generation, increased macrophage infiltration of tumor tissue, rendering tumor cells more sensitive to gemcitabine chemotherapy." (PMID 40486886, 2025). "Furthermore, engineered CD24-targeted CAR-NK cells effectively and specifically killed the CD24-positive ovarian cancer cell lines OVCAR-3 and SKOV3 both in vitro and in vivo." (PMID 40705122, 2025). "A range of malignancies, including ovarian cancer, small cell lung cancer, urothelial cancer, liver cancer, cholangiocarcinoma, colorectal cancer, and esophageal squamous cell carcinoma, have been shown to overexpress CD24 in tumor tissues." (PMID 40486886, 2025). "They collected ascites samples of ovarian cancer patients before and after treatment and observed that increased levels of exosomal EpCAM and CD24 in samples after treatment were associated with nonresponding patients." (PMID 38928484, 2024). "Therefore, like CD244, CD24 is also likely to exhibit dual opposing functions depending on the molecular basis of ovarian cancer cells." (PMID 38360723, 2024). "CD24-miR-130a/301a-CDK19 signaling axis could be a prognostic marker for or a potential therapeutic target against ovarian cancer recurrence." (PMID 38360723, 2024). "The components of the CD24-miR-130a/301a-CDK19 signaling axis may be correlated with the poor prognosis of ovarian cancer patients." (PMID 38360723, 2024). "Recent studies have found that CD24 on ovarian cancer (OC) and triple-negative breast cancer cells interacts with the inhibitory receptor sialic-acid-binding Ig-like lectin 10 (Siglec-10) on tumour-associated macrophages (TAMs) to inhibit phagocytosis by macrophages." (PMID 38702326, 2024). "Our results showed that CD24 expression may induce a cellular quiescence-like state and resistance to platinum-based chemotherapeutic agents in ovarian cancer via miR-130a and 301a upregulation." (PMID 38360723, 2024). "CD24 functions as an immune checkpoint in ovarian cancer, where cells evade phagocytosis by macrophages through the interaction of CD24 molecules with the inhibitory receptor sialic acid-binding immunoglobulin-like lectin 10 (Siglec-10) on tumor-associated macrophages." (PMID 40836974, 2024).
ovarian carcinoma (continued). "Patients with triple-negative breast cancer (TNBC) and ovarian cancer have a fraction of tumor-associated macrophages (TAM) in the tumor microenvironment (TME) that highly express Siglec-10, the main ligand for CD24, which is widely expressed by B cells, activated T cells, and monocytes." (PMID 38279998, 2024). "In this study, we mined the miRNAs depending on CD24 expression from primary ovarian cancer cells." (PMID 38360723, 2024). "In ovarian cancer, CD24 has been shown to be expressed in epithelial CSCs." (PMID 39546568, 2024). "CD24 expression reduced colony forming ability of ovarian cancer cells." (PMID 38360723, 2024). "Our results suggest that the CD24-miR-130a/301a-CDK19 signaling axis could be a prognostic marker for or a potential therapeutic target against ovarian cancer recurrence." (PMID 38360723, 2024). "CD24 expression slowed the growth rate of ovarian cancer cells." (PMID 38360723, 2024). "Downregulation of either CD24 or Siglec-10, as well as blockade of the CD24-Siglec-10 axis via monoclonal antibodies, enhanced the phagocytosis of CD24-expressing ovarian cancer cells and resulted in a macrophage-dependent reduction in tumor growth in vivo and increased survival." (PMID 39432076, 2024). "CD24 expression induced the cellular quiescence-like state in ovarian cancer cells." (PMID 38360723, 2024). "CD24‐mediated signalling route for ovarian cancer stem‐like phenotype manifestation." (PMID 38030594, 2024). "Data above has demonstrated that knockdown of CD24 by shRNA therapies might be a potential therapeutic approach against human ovarian cancer." (PMID 38881902, 2024). "CD24 plays a dual role in the growth of ovarian cancer cells." (PMID 38360723, 2024). "Similar to CD47 and PD-L1, the anti-phagocytic surface protein CD24 in ovarian cancer cells acts as the primary innate immune checkpoint, binding to the inhibitory receptor siglec-10 on TAMs’ surfaces to send out a “don't eat me” signal, thereby helping cancer cells escape from the immunity." (PMID 39003350, 2024). "A study in ovarian cancer might offer valuable insights for us, as it revealed that EVs derived from TAMs encapsulate GATA-binding protein-3 (GATA3), which promotes chemotherapy resistance in ovarian cancer cells to DDP by upregulating the CD24/Siglec-10 axis." (PMID 38816455, 2024). "The device was used to detect exosome subtypes expressing CD24, EpCAM, and FRalpha proteins in 2 μL plasma samples from 20 ovarian cancer patients and to suggest exosomal FRalpha as a promising biomarker in the early detection and monitoring of ovarian cancer progression." (PMID 38793203, 2024). "The correlation between CD24 and CSC phenotypes led us to assume that CD24 may induce CSC phenotype manifestation in ovarian cancer cells via CD24-regulated miRNAs." (PMID 38360723, 2024). "Peter Altevogt found that Ovarian carcinoma ascites derived exosomes contain CD24, which might enhance the tumor invasion ability into the stroma." (PMID 37359556, 2023). "The codon-optimized third-generation CAR containing the highly active single chain variable fragment (scFv) “SWA11” against CD24 could engineer the NK cells with high cytotoxic activity against CD24-positive ovarian cancer cell lines." (PMID 37359556, 2023). "These types of evidence strongly support that the blockade of CD24/Siglec-10 immune checkpoint pathway might provide an effective therapeutic target to improve anti-tumor immunity in the aspect of breast and ovarian cancer hosts." (PMID 36109471, 2023). "The team’s findings suggest that antibodies that block CD24 and Siglec10 interactions can enhance macrophages’ effectiveness in killing tumor cells in refractory ovarian cancer, which is common in women, and triple-negative breast cancer, which is difficult to immunotherapy." (PMID 37484024, 2023). "Nowadays, CD24 has been identified as a promising focus for targeting therapy of ovarian cancer." (PMID 37359556, 2023).